KLF4 (KLF transcription factor 4)
Diseases named in the same sentence as KLF4 in open-access papers (continued):
Sharing a sentence is not in itself a finding about the gene and the disease.
cancer (continued). "CSCs reside among other more differentiated cancer cells, are resistant to apoptosis and their self-renewal is based on transcription factors similar to those of adult and embryonic stem cells such as Oct4, Nanog and Klf-4." (PMID 26042045, 2015). "In this connection, HIF-2α may act through up-regulation of KLF4, Sox2 and Octamer-4, to favor de-differentiation and confirmation of stem-cell properties of putative cancer stem cells." (PMID 25544768, 2015). "IL6ST, KLF4 and PGRMC2 have been linked to cancer pathogenesis, and downregulation of their mRNA expression by miR-142-3p may therefore be worth elucidating in future studies." (PMID 26657485, 2015). "Recent studies have shown that CTNNB1 could regulate Tert expression through the interaction with Klf4, and thereby telomere length, which could be critical in human cancer." (PMID 24465727, 2014). "The success of these therapies may in part be due to removal of aberrant hypermethylation at CpG islands within promoter regions of key cancer genes including KLF4, RUNX3, and RSU1 identified as hypermethylated in our data." (PMID 25294808, 2014). "Additionally, a promoting interaction between KLF4 and CDH1 (E-cadherin) has been described, hereby driving cancer cells into an EMT-program through loss of KLF4." (PMID 25593984, 2014). "In addition to regulating many important physiological processes, KLF4 has been shown to play a role in pathologic conditions such as cancer and inflammation." (PMID 25060774, 2014). "Although hypermethylation and loss-of-heterozygosity have been reported as causative events for KLF4 downregulation in the intestinal epithelium, the molecular mechanisms responsible for KLF4 downregulation in cancer of other epithelial tissues have been poorly explored." (PMID 25181544, 2014). "Interestingly, the presence of HGF in the proximity of cancer cells, triggers KLF4 to inhibit CDH1 transcription." (PMID 24429391, 2014). "KLF4 is also involved in cancer stem cell or stem cell renewal." (PMID 23861801, 2013). "Since genetic instability plays a crucial role in the development and progression of human cancer, we sought to determine whether re-expression of Klf4 in Klf4−/−MEFsMay correct the observed genetic instability in these cells." (PMID 23919723, 2013). "Although the detailed mechanisms by which KLF4 influences cancer development and progression remain unclear, evidence has suggested that the altered KLF4 expression affects G1/S or G2/M phase of the cell cycle." (PMID 23861801, 2013). "The reprogramming factors OCT4, SOX2, NANOG, KLF4, c-MYC, and LIN28 have also been suggested to be oncogenes and may be implicated in the development of several cancers." (PMID 24040120, 2013). "As noted in the rat model, the inverse association between miR-206 and KLF4 was not always apparent; for example, Case 9 exhibited low relative expression of both miR-206 and KLF4 in the cancer compared with the patient-matched control." (PMID 23006636, 2012). "It was also established that induced pluripotent stem (iPS) or pluripotent cancer (iPC) cells could be generated by co-transfection of Sox2 cDNA with other transcription factors such as Oct4, Klf4 and c-Myc into fibroblast or cancer cells." (PMID 22615765, 2012). "Among Klf family members, Klf4 has attracted recent attention because of its capability, in concert with other factors, to reprogram cell fate determination, as well as promoting or suppressing cancer development in a context dependent manner." (PMID 20442780, 2010). "At the post-transcriptional level, KLF4 mRNA stability and translation efficiency are primarily regulated by non-coding RNAs, while RNA methylation modifications also play a crucial role, influencing RNA localization, splicing, translation, and degradation, which in turn affect cancer progression." (PMID 39995670, 2025).
cancer (continued). "Understanding the connection of KLF4 isoforms to cellular plasticity and its role in mediating immunological memory in innate immune cells may have significant therapeutic implications in immune-related disorders and cancer." (PMID 40552304, 2025). "We first investigated whether KLF4 regulates cell proliferation and migration in cancer cells." (PMID 38879589, 2024). "Interestingly, Sox2 and Klf4 have been pointed out as the relevant reprogramming factors inducing leukemic apoptosis, exemplifying the context dependent effect of the Yamanaka factors in cancer cells of different origin." (PMID 39587064, 2024). "Therefore, small molecule inhibitors or combination chemotherapeutic agents designed to target KLF4 protein in precancerous lesions may have an effective role in cancer prevention and intervention." (PMID 37031197, 2023). "Therefore, it is premature to consider KLF4 as a general target for cancer therapy." (PMID 37031197, 2023). "However, KLF4 can also act as an initiator of cancer cell proliferation in bladder cancer." (PMID 36761967, 2023). "However, it is not clear whether there is an interaction between the two NLSs affecting the nuclear or cytoplasmic localization of KLF4, especially the role in different types/subtypes of cancers." (PMID 37031197, 2023). "Differences in the cancer types/subtypes may render KLF4 diverse roles in different stages of PDA." (PMID 37031197, 2023). "KLF4, a member of the Yamanaka factor family (OCT3/4, SOX2, KLF4, and c-MYC, collectively referred to as OSKM), is known to play a crucial role in embryonic stem cells and is also implicated in maintaining stemness and EMT processes in the context of cancer stem cell models." (PMID 37762678, 2023). "Furthermore, KLF4 could sensitize the therapeutic response to many known drugs, e.g., cetuximab, cisplatin and mesalazine, in the treatment of cancer, suggesting the combined use of APTO-253 with other anticancer drugs in future clinical trials." (PMID 36936440, 2023). "Therefore, the anti- or pro-cancer roles of KLF4 are unpredictable." (PMID 37031197, 2023). "In conclusion, our results identified that miR-7-5p was downregulated in radioresistant cells and tissues, and enforced expression of miR-7-5p could increase radiosensitivity by directly targeting KLF4 that inducing impaired cancer stem cell properties in CRC cells." (PMID 36732504, 2023). "In addition, the effects of KLF4 vary from the stages of cancers." (PMID 37031197, 2023). "IPSs can be derived from mature cells, or even cancer cells, by forcibly expressing stem cell markers such as Oct4 (octamer-binding transcription factor 4), Sox2 (sex determining region Y-box 2), Myc (Myelocytomatosis proteins), and Klf4 (Krüppel like factor 4)." (PMID 35371349, 2022). "These CTCs expressing IGFBP5 also had increased expression of stem cell associated genes aldehyde dehydrogenase 1A2 (ALDH1A2) and Kruppel-like factor 4 (Klf4), which could indicate a cancer stem-like cell phenotype, a state thought to modulate the ability of cancer cells to seed new tumors." (PMID 36465383, 2022). "Transcription factor genes (OCT4, KLF4, SOX2, MYC, NANOG, and REX1) and cell surface markers (CD133, LGR5), which are associated with embryonic stem cells, induced pluripotent stem cells, and cancer stem cells, have been selected for measuring expression levels from the selected tissues." (PMID 34452555, 2021). "Moreover, downregulation of DNMT1 could suppress cancer cell viability, migration and invasion through upregulation of KLF4 expression." (PMID 33596966, 2021). "Next, we analyzed whether KLF4 is involved in NOXA expression in human cancers and normal tissues." (PMID 33918002, 2021). "In a previous study, it was shown that those subpopulations of cancer cells exhibiting high expression of KLF4 and/or Oct4 and low expression of Sox2 produced much more colonies than subpopulations with high Sox2 expression and lower KLF4 and/or Oct4 expression." (PMID 32138176, 2020).
cancer (continued). "Further, KLF4 is one of the key factors that is used in induced pluripotent stem cell (iPSC) technology; therefore, it may also be involved in the regulation of cancer stemness." (PMID 33052880, 2020). "Finally, YY1 may positively regulate the expression of another transcription factor KLF4, showing a dual role in cancer, with a possible prognostic value." (PMID 32899428, 2020). "Moreover, we observed that expression of wild‐type KLF4, but not the KLF4 PARylation‐deficient mutant, improves cancer cell survival in the presence of olaparib." (PMID 33231937, 2020). "Therefore it appears that increasing KLF4 expression might sensitize drug-resistant cancer cells to chemotherapy." (PMID 33266506, 2020). "However, Klf4-deletion has also been shown to either directly underpin cancer development or progression, or disrupt processes relevant for cancer development or progression, in non-epithelial tissues, typically (but not exclusively) in the presence of a genetic (or other) compounding stressor." (PMID 33266506, 2020). "Furthermore, it has been reported that in several types of cancers, KLF4 may be a context-dependent oncogene, switching by a regulation on the expression levels of cell-cycle regulator p21." (PMID 29062163, 2017). "In addition, KLF4 has been identified as anti-oncogene and oncogenes in various kinds of cancers." (PMID 28938633, 2017). "Therefore, future studies should analyze KLF4(FL) as well as KLF4α levels in cancer patients." (PMID 27323810, 2016). "It is, therefore, not surprising that KLF4 over-expression is associated with cancer." (PMID 27148537, 2016). "Except for KLF4, overexpression of DEC1, p21 and ING1, which could induce cell senescence, are associated with a better survival in certain cancers, indicating that senescence may also have a protective function in cancer development." (PMID 27531889, 2016). "However, KLF4 was recently found to act as an oncogene in some specific cancers." (PMID 26517087, 2015). "Finally, KLF4 plays a key role in cancer progression and development." (PMID 26517087, 2015). "Thus, KLF4 has multiple, context-dependent roles in cancer development and progression." (PMID 26517087, 2015). "Also, the expression of KLF4 is downregulated in several cancer types." (PMID 25879941, 2015). "Furthermore, down-regulation of Sp1 may suppress the acquisition of cancer stem cell phenotypes through the reduced expressions of SCTFs, including Bmi1, c-Myc and KLF4." (PMID 25099028, 2014). "Notably, the expression of Klf4 is down-regulated in several different cancer types." (PMID 23451207, 2013). "Thus, an interesting issue is whether KLF4 acts still as a cancer suppressor in colon CSCs or as a critical factor involved in colon CSCs self-renewal." (PMID 23418515, 2013). "However, the combined siRNA-mediated knockdown of Klf4 and Sp3 resulted in consistent up-regulation of Notch1 expression in both HKCs and cancer cells (HeLa and SCC13 cells), with the concomitant knock-down of Sp1 having no additional effects (C and data not shown)." (PMID 20442780, 2010). "However, Notch1 expression can also become aberrantly suppressed by Klf4 during cancer development." (PMID 20442780, 2010). "Modulating KLF4 activity offers a potential strategy to alter the abundance and functional properties of DC2 subsets in cancer vaccines or immunotherapy, aiming to enhance antigen presentation." (PMID 41532367, 2026). "Cellular localization of KLF4 and CTNNB1 protein expression in cytoplasm and nucleus with morphological changes of the cancer cells revealed the onset of programmed cell death." (PMID 42224286, 2026). "PDAC cancer stem cell markers including CD44, MET, CD133, FUT4, ACVR1, mTOR, and KLF4 were positively related to IARS2 expression." (PMID 40092487, 2025). "HK2 also regulates stemness properties of cancer cells by upregulating key stemness genes such as NANOG, SRY-Box 9 (SOX9), CD117, octamer-binding transcription factor 4 (OCT4), and Krüppel-like factor 4 (KLF4)." (PMID 40427188, 2025).
cancer (continued). "The hypoxia-associated signaling pathways can trigger the HIF-dependent expression of molecules like KLF4, MYC, OCT4, SOX2, and NANOG, which can enhance cancer stemness and inhibit cancer cell differentiation." (PMID 39928285, 2025). "This review explores how distinct KLF4 isoforms, generated through context-specific splicing events, may act as molecular switches modulating myeloid plasticity and trained immunity with far-reaching implications for inflammation, cancer, and regenerative medicine." (PMID 40552304, 2025). "The upregulated ABCB1, ZEB1, and CD44 were engaged in microRNA regulation in cancer, SOX2 and KLF4 were engaged in pluripotency of stem cells, and TWIST1 and CD44 contributed to proteoglycans in cancer." (PMID 40251609, 2025). "Most notably, many of these early response alterations in the cancer cells are known pro‐angiogenic transcripts, including ITGA2, CLDN12, SMAD7, MET, KLF4, ID3 and ID1." (PMID 40116596, 2025). "We next generated a dormancy gene signature from our findings that included the expression levels of SLURP1, INFGR2, KLF4, and CD200 in cancer cells along with CD200R1 in NK cells and tested for links to immunotherapy responses." (PMID 40568095, 2025). "Targeting KLF4 ubiquitination pathways holds promise for developing strategies to manipulate CSC characteristics and advance cancer therapies." (PMID 40034124, 2025). "The cancer cell stemness reprogramming factors OCT4, KLF4 and c‐MYC and the stem cell marker CD44 were significantly increased in Huh7 cells on the 14th day after HBx overexpression." (PMID 40717222, 2025). "Given the importance KLF4 in regulating a hillock-like cell state and its regulatory role in a variety of cancers, we sought to determine if TMPRSS11B is induced by KLF4." (PMID 41214366, 2025). "CSC transcription factors (such as SOX2, OCT4, KLF4 and CD44) are important marker of cancer and normal stem cells." (PMID 39611488, 2025). "Furthermore, based on our analysis of DepMap data, targeting KLF4 in ARID1A-deficient cancer cells does not appear to influence the fitness of ARID1A mutant cell lines, further highlighting the specificity of the effect of loss of KLF5 on ARID1A -deficient cells." (PMID 39779698, 2025). "Increased KLF4 expression augments the self-renewal ability and invasiveness of cancer stem cells (CSCs), but miR-7 overexpression markedly diminishes CSC metastatic activity by directly interacting with the 3′UTR of KLF4 mRNA." (PMID 40710326, 2025). "Among all overlapping cancer genes regulated by these two eccMIR clusters, the downregulated expression of PIM1, KLF4, and FBLN2 was confirmed via RT-qPCR." (PMID 39920810, 2025). "Among of them, SLC12A5, MYO1B, FBN1, ITGAV, KLF4 and USP28 were more reported to effect cell proliferation and migration in human cancers." (PMID 39951205, 2025). "Krüppel-like factor 4 (KLF4) is a transcription factor that facilitates the transcription of the tumour suppressor TIMP3 by directly binding to the TIMP3 promoter, inhibiting cancer progression in vitro and in vivo." (PMID 38542164, 2024). "The pluripotent transcription factors KLF4, NANOG, OCT4, and SOX2 are essential for maintaining cell stemness in cancer." (PMID 38233377, 2024). "Krüppel-like factor 4 (KLF4) belongs to a family of transcription factors (TFs) playing a variety of functions and having a significant potential in cancer development and progression." (PMID 39135777, 2024). "For example, in silico analyses were performed for some alternatively spliced proteins with reported antagonistic functions in cancer, including BRD4, KLF4, and UHRF2." (PMID 38539439, 2024).
cancer (continued). "KLF4 and MYC are also cohesively involved in the transcriptional regulation of stem cells, development and cancer." (PMID 38561775, 2024). "Hypoxia and HIF1 are generally known to be important in cancer stem cell development, inducing, for example, the expression of OCT4, SOX2, NANOG and Krüppel-like factor 4 (KLF4) as stem cell markers." (PMID 38773108, 2024). "Taken together, these results revealed that miR-7-5p decreased the cancer stemness and enhanced radiosensitivity of CRC cells by targeting KLF4." (PMID 36732504, 2023). "OCT3/4, SOX2, Nanog, and KLF4 are CSC transcription factors that are involved in carcinogenesis and have been used to detect cancer stem cell subpopulations in various types of cancer." (PMID 37070617, 2023). "A series of in vitro loss- and gain-of-function studies demonstrated that miR-7-5p suppressed cancer cell stemness and enhanced radiosensitivity in CRC by targeting KLF4." (PMID 36732504, 2023). "MUC1-C induces the OCT4, SOX2, KLF4, MYC (OSKM) pluripotency factors in TNBC and other cancer cells." (PMID 37821650, 2023). "The last decade has brought much information regarding the roles KLF4 and KLF5 play in cancer development and progression." (PMID 37173904, 2023). "During cellular autophagy/lysosomal degradation, MCPIP1 negatively regulates cancer cell apoptosis induced by death receptor 5 (DR5) transcription and DR5 activation, suggesting that KLF4 is involved in a novel pathway of apoptosis." (PMID 36761967, 2023). "It is important for promoting the CSC phenotype, prompting de-differentiation of cancer cells to CSCs, as well as inducing the expression of pluripotent stem cell markers, OCT4, NANOG, SOX2, KLF4, c-MYC." (PMID 37614497, 2023). "In other papers suggesting a link between OTUD1 and cancer, OTUD1 reportedly deubiquitinates and stabilizes Krüppel-like factor 4 (KLF4), a zinc finger transcription factor that regulates proliferation, differentiation, apoptosis, and reprogramming." (PMID 36829909, 2023). "SETD5 overexpression causes the upregulation of PI3K-AKT pathway-related genes and cancer stem cell (CSC) markers such as CD133, Kruppel-like factor 4 (KLF4), and estrogen-related receptor beta (ESRRB), leading to the gain of stem cell-like phenotypes." (PMID 37963940, 2023). "SOX2 was required in early-stage ADC and SCLC, whereas OCT3, KLF4, and NANOG participate other cancer types." (PMID 36717865, 2023). "However, whether KLF4 is cancer-promoting or cancer-suppressing remains a mystery." (PMID 37031197, 2023). "Stem-cell-related factors, such as SOX2, KLF4, NANOG, OCT4, ALDH1, and ALDH2, have been reported to be vital for maintaining cell self-renewal traits in many types of cancer." (PMID 36674577, 2023). "This response triggers several functions, including the regulation of stemness through transcription factors (such as SOX2, KLF4, NANOG, MYC, and OCT4) that promote cancer cell survival and sometimes correlate with poor prognosis and tumor progression." (PMID 37371030, 2023). "KLF4 is a critical transcription factor in embryonic stem cells and is important for CSC maintenance of cancer stem cells." (PMID 37762678, 2023). "Embryonic stem cell (ESC) transcription factors such as NANOG, Oct-4, KLF4, and SOX-2 are reported to be involved in the stemness features of cancer cells, including in the process of dormancy/reactivation induced by chemotherapy." (PMID 37176108, 2023). "The ‘Yamanaka factors’ OCT3/4, SOX2, KLF4, and c-MYC (OSKM) are essential for maintaining the characteristics of cancer stem cells." (PMID 37762678, 2023).